IL17A (interleukin 17A)
Diseases named in the same sentence as IL17A in open-access papers (continued):
Sharing a sentence is not in itself a finding about the gene and the disease.
disseminated candidiasis (13 papers, 2009 to 2025). Systemic candidiasis occurs when Candida yeast enters the bloodstream and may spread (becoming disseminated candidiasis) to other organs, including the central nervous system, kidneys, liver, bones, muscles, joints, spleen, or eyes. "It was shown that a deficiency in IL-17A response results in increased susceptibility to oropharyngeal and disseminated candidiasis." (PMID 30409128, 2018). "The lack of a requirement for IL-17A to mediate normal host defense against disseminated candidiasis likely reflects the ability of IL-17F, which also activates the common IL-17 receptor, to complement an IL-17A deficiency." (PMID 20041174, 2009). "IL-17RA−/−, RORγt−/−, and IL-17A−/− mice are susceptible to disseminated candidiasis." (PMID 26336150, 2015). "IL-17RA-/- and IL-17A-/- mice show elevated susceptibility to disseminated candidiasis." (PMID 25474407, 2014). "The interaction between IL-17A and IL-17A receptor (R) signaling in both hematopoietic and nonhematopoietic cells is protective against different stages of disseminated candidiasis." (PMID 41229429, 2025). "In addition to a critical role in protecting against oral mucosal candidiasis, IL-17RA and IL-17A are protective in an intravenous model of disseminated candidiasis." (PMID 25849644, 2015). "Our data suggest a model whereby pathology results from excessive Th17-cell responses associated with Foxp3 induction in disseminated candidiasis, while not excluding a role for lower levels of IL-17A in protection from the fungus." (PMID 24435677, 2014). "Collectively, these results indicate that Th17 cells/IL-17A are not necessary for normal murine host defense against disseminated candidiasis." (PMID 20041174, 2009).
enteritis (13 papers, 2014 to 2025). Inflammation of the small intestine. "The results suggested that IEt alleviated radiation-induced enteritis, as evidenced by improved colonic structural integrity, decreased levels of pro-inflammatory factors like IL-17A, and the restoration of intestinal microecological and metabolic balance." (PMID 40730483, 2025). "While deletion of IL-17A from A20ZF7/ZF7 mice exacerbates enteritis, deletion of IL-22 abrogates intestinal epithelial cell hyperproliferation, barrier dysfunction, and alarmin expression." (PMID 40892518, 2025). "Luteolin has high anti-inflammatory activity and can effectively inhibit the expression of NLRP3 by inhibiting IL-17A signal in enteritis tissue." (PMID 33149752, 2020). "The number of CD4+CD25+Foxp3+ Tregs and CD4+IL-17A+ Th17 cells in the mesenteric lymph nodes differed significantly from the enteritis and Tregs-inhibiting groups (p<0.05)." (PMID 30364052, 2018). "Here, using a mouse model of T cell activation-induced enteritis, we show IL-17A may be involved in GI hypermotility in the model by inducing hypercontractility in SMCs." (PMID 24796324, 2014). "Small intestines from A20ZF7Il17a–/– mice exhibited more (rather than less) severe enteritis than those from IL-17A–competent A20ZF7 mice." (PMID 40892518, 2025). "Using the mouse model of T cell activation-induced enteritis, we investigated whether enhancement of smooth muscle cell (SMC) contraction by interleukin (IL)-17A is involved in postinflammatory GI hypermotility." (PMID 24796324, 2014). "Hence, IL-17A plays a protective rather than proinflammatory role in enteritis in A20ZF7 mice." (PMID 40892518, 2025).
fibrosarcoma (13 papers, 2008 to 2022). A malignant mesenchymal fibroblastic neoplasm affecting the soft tissue and bone. "Furthermore, decreased efficacy of anthracyclines and oxaliplatin was observed in mouse fibrosarcoma allografts in IL-17A knockout mice, a phenotype that was rescued upon adoptive transfer of γδ T cells with normal IL-17 production." (PMID 35924165, 2022).
Pleural effusion (13 papers, 2011 to 2025). The presence of an excessive amount of fluid in the pleural cavity. "In contrast, IFN-γ, GM-CSF, IL-17A levels were lower in pleural effusion than in plasma (p ≤ 0.0005)." (PMID 39737183, 2024). "IL17A levels were correlated with some clinical characters, such as refractoriness and pleural effusion." (PMID 29021577, 2017). "Lower IL17A levels were more likely to be found in refractory MPP children or in MPP children with pleural effusion." (PMID 29021577, 2017). "In fact, our findings revealed a significant positive correlation between DN T cells and the cytokines IL-17A and IFN-γ in pleural effusions, indicating the presence of Th-like DN in PE." (PMID 39737183, 2024). "The results showed that the percentages of Th17(IL-17A+) cells in pleural effusion of TPE were significantly higher than those in the blood of TPE patients and pleural effusion of TE patients, consistent with literature reports." (PMID 34237073, 2021). "We put forward the hypothesis that low IL17A levels in BALF may suggest severe MPP in children and more likely to become MPP with pleural effusion and refractory MPP." (PMID 29021577, 2017). "The expression of IL17A in children with pleural effusion was obviously lower than that without pleural effusion." (PMID 29021577, 2017). "Furthermore, greatly decreased levels of IL17A were also found in refractory MPP group and MPP with pleural effusion group." (PMID 29021577, 2017). "Higher IL17A expression in BALF is correlated with general MPP and MPP without pleural effusion; lower IL17A expression in BALF is correlated with refractory MPP and MPP with pleural effusion." (PMID 29021577, 2017). "Moreover, the protein levels of IL17A in BALF were significantly lower in MPP with pleural effusion group comparing to that in MPP without pleural effusion group." (PMID 29021577, 2017). "We also checked IL-17A and IL-22 production in MAIT cells by intracellular staining with specific antibodies and flow cytometry, and both of them were minimal in MAIT cells but were clearly detected in other cells from pleural effusions (data not shown)." (PMID 27586092, 2016).
primary biliary cirrhosis (13 papers, 2011 to 2025). "Compared with healthy people, primary biliary cholangitis patients had more iNKT cells, which produced high levels of IL-17A and promoted the progression of PBC-related fibrosis." (PMID 37539053, 2023). "Furthermore, IL-2Rα KO mice lost the repressive effect of IL-2 on Th17 cells, showed elevated levels of serum IL-17A, and finally suffered from primary biliary cirrhosis (PBC)." (PMID 26325187, 2015). "Recently, it has been proposed that the IL-17A-mediated signaling and EMT of intrahepatic biliary epithelial cells are involved in the pathogenesis of primary biliary cirrhosis (PBC)." (PMID 38202170, 2023).
pustular psoriasis (13 papers, 2013 to 2025). "The time from the initiation of IL-17A inhibitors to the onset of pustular psoriasis, 1 case occurred at 1 month, 1 case at 2 months, 2 cases at 3 months, 2 cases at 4 months, 2 cases at 9 months, and 1 case at 16 months." (PMID 38695018, 2024). "Interestingly, case reports have indicated that different types of IL-17A inhibitors can induce pustular psoriasis, which is a well-known rare paradoxical reaction of anti TNF-α therapies." (PMID 38695018, 2024). "This IL-17A–induced Th17 signature was not related to the neutrophil accumulation nor the disease activity in pustular psoriasis." (PMID 38448036, 2024). "Furthermore, skin explants of pustular psoriasis cultured with a neutralizing anti-IL-26 mAb but not anti-IL-17A mAb completely inhibited the expression of CXCL1, CXCL8, and IL1A, confirming the specific role of IL-26 as a driver of pathogenic autoinflammation circuits." (PMID 38448036, 2024).
SAPHO syndrome (13 papers, 2021 to 2025). SAPHO syndrome (acronym for Synovitis, Acne, Pustulosis, Hyperostosis and Osteitis) is an auto-inflammatory disease, mainly characterized by the association of neutrophilic cutaneous involvement and chronic osteomyelitis. "This case illustrates the effectiveness of upadacitinib, a selective JAK1 inhibitor, for the rapid resolution of cutaneous and articular symptoms of SAPHO syndrome following unsuccessful IL-17A inhibition, offering valuable insights for management of refractory SAPHO syndrome." (PMID 41341579, 2025).
alopecia (12 papers, 2019 to 2025). Hair loss usually from the scalp. "Six studies utilizing IL-17 inhibitors such as secukinumab and ixekizumab, which block IL-17 A, and brodalumab, which blocks the IL-17 receptor, in the treatment of scarring alopecia were identified." (PMID 40488905, 2025). "Our results indicated that as the severity of alopecia increased from mild to severe, there was a corresponding increase in the levels of IL-6, TNF-α, IL-17A, and IL-21." (PMID 41002719, 2025).
aneurysm (12 papers, 2019 to 2025). Bulging or ballooning in an area of an artery secondary to arterial wall weakening. "There also appears to be an interplay between the Th17/IL-17 axis and vasculopathy in humans: murine models demonstrate aneurysm formation from IL-17A blockade, while blocking HIF-1α causes coronary vessel abnormalities and prevents Th17 lymphocyte differentiation." (PMID 33932191, 2021). "In some AAA patients, plasma levels of IFN-γ, IL-17A, and C-reactive protein are positively correlated with the cross-sectional area of AAA, while IL-10 is positively correlated with the growth rate of the aneurysm, and increased CRP levels indicate an increased risk of death in AAA patients." (PMID 38111889, 2023). "In a mouse model (AngII infusion in ApoE−/− animals on high-fat diet), IL-17A was found to promote aortic superoxide production as well as aortic leukocyte and dendritic cell infiltration, but did not seem to affect aneurysm formation." (PMID 31989839, 2020).
cerebral infarction (12 papers, 2014 to 2025). An ischemic condition of the brain, producing a persistent focal neurological deficit in the area of distribution of the cerebral arteries. "ELISA results demonstrated decreased levels of IL-17A in both peripheral blood and cerebral infarction homogenate of the P2X7-KO group." (PMID 40948793, 2025). "The use of LIPUS or IL-17A mAb alone or a combination of both resulted in a significant reduction in cerebral infarct size on day 7 postoperatively." (PMID 40290135, 2025). "Meanwhile, ELISA results demonstrated that the IL-17A level was significantly decreased in cerebral infarction homogenate and slightly decreased in peripheral blood without significance of the P2X7-KO group." (PMID 40948793, 2025). "Several studies have indicated that IL-17A levels are elevated in ischemic brain tissue and the peripheral blood of cerebral infarction patients." (PMID 24991091, 2014). "Meanwhile, although we have demonstrated the significance of IL-17A, we also observed reduced levels of IL-1β and CCL2 in the cerebral infarction homogenates of P2X7-KO mice following tMCAO." (PMID 40948793, 2025).
chronic hepatitis C (12 papers, 2013 to 2025). "However, a study conducted by Baskic and collegues, 2017 investigating the cytokine profile in chronic hepatitis C demonstrated that median levels of IL-17A were lower in patients with HCV than in controls." (PMID 33435966, 2021).
coronary atherosclerosis (12 papers, 2015 to 2025). Atherosclerosis of the coronary vasculature. "Therefore, we cannot establish that the expression of IL17-A is enough to drive the coronary atherosclerosis." (PMID 38132456, 2023). "Furthermore, the presence of both IL-17A and IFN-γ in clinical specimens of coronary atherosclerosis and the presence of IL-17A/IFN-γ double producer T cells within coronary plaques were reported." (PMID 25830298, 2015).
crescentic glomerulonephritis (12 papers, 2015 to 2025). A histopathologic term for a pattern of diseases characterized by extensive crescent formation in the glomeruli; patients present clinically with rapid deterioration of renal function, and possible progression to end-stage renal failure within weeks or months. "IL-17A, for instance, is implicated in the immunopathogenesis of crescentic glomerulonephritis (GN) by promoting neutrophil recruitment, and it plays a pivotal role in MPO-ANCA GN pathogenesis by fostering the development of MPO-specific αβ T cells." (PMID 38354117, 2024). "In Crescentic glomerulonephritis, renal IL-17A-producing γδ T cells were found to be the main contributor in the early inflammatory response by promoting kidney injury." (PMID 34335608, 2021). "In the nephrotoxic nephritis (NTN) mouse model for crescentic glomerulonephritis, we showed that Il17c is upregulated as early as 12 h after induction of the disease, while Il17a and Il17f expression starts after a couple of days." (PMID 32174926, 2020). "Indeed, blockade of IL-17A with an antibody abolished the difference in renal damage between wildtype and Il17c−/− mice in a model for crescentic glomerulonephritis." (PMID 32174926, 2020). "Accordingly, patients with ANCA-associated vasculitis presented elevated serum levels of IL-17A and other Th17-related cytokines, such as IL-23, whereas in ANCA-associated crescentic glomerulonephritis patients, only serum IL-17C but not IL-17A, F, or E levels were increased." (PMID 32987705, 2020). "Mice lacking IL-17A failed to develop crescentic glomerulonephritis while IL-17A competent T-cells transferred from MPO-immunized mice induced renal injury." (PMID 40821760, 2025).
gastric tumors (12 papers, 2013 to 2025). "In the present study, we have addressed the role of IL-17A in H. pylori-associated gastric carcinogenesis and the precise mechanisms underlying its contribution to tumor development using an H. pylori-induced mouse gastric tumor model and human GC cell lines." (PMID 36125689, 2023). "While IL-17A is clearly increased in human gastric tumors, its specific contribution to tumor pathogenesis remains elusive." (PMID 36125689, 2023). "Finally, functional validation through CCK-8 proliferation assays, wound Healing assays, and transwell assays conclusively demonstrated the tumor-promoting effects of IL-17A and IL-26 on gastric tumor cells." (PMID 40452847, 2025). "Histopathologically, the overall incidence of stomach tumors was lower in IL-17A KO than WT mice." (PMID 36125689, 2023). "We initially evaluated IL-17A expression in gastric tumors of WT mice infected with H. pylori." (PMID 36125689, 2023). "Then, neutrophils induce the polarization of the IL-17A-generating Th subsets in a B7-H2-dependent manner, where polarized IL-17A-generating Th cells can be able to wield protumorigenic roles through IL-17A, thereby leading to gastric tumor onset and progression." (PMID 36091114, 2022). "Deletion of IL-17A suppressed MNU and H. pylori-induced gastric tumor development accompanied by a decrease in gastric epithelial cell growth, oxidative stress, and expression of gastric epithelial stem cells markers." (PMID 36125689, 2023).
Graves disease (12 papers, 2014 to 2025). Graves' disease is an autoimmune disorder that leads to overactivity of the thyroid gland (hyperthyroidism).It is caused by an abnormal immune system response that causes the thyroid gland to produce too much thyroid hormones. "Serum cytokine levels (including IL-6, IL-9, IL-17A, IL-17F, and IL-22) exhibited significant differences between healthy subjects and patients with newly diagnosed hyperthyroid Graves’ disease (GD) under varying serum iodine concentration (SIC)." (PMID 40895623, 2025). "Direct IL-17A stimulation of Graves’ disease thyrocytes resulted in abnormal proliferation and hyperfunction." (PMID 40895623, 2025).
leukocytosis (12 papers, 2013 to 2025). "The authors hypothesized that the present CD4+ T cells were able to lower the bacterial load in the milk of infected udder quarters, e.g., through leukocytosis caused by their production of IL-17A and INF-γ." (PMID 35681803, 2022). "After cow immunization with ovalbumin, IL-17A was present in the milk of all the high-responder cows right after milk leukocytosis developed." (PMID 35335696, 2022). "The magnitude of the local inflammatory reaction, assessed through milk leukocytosis, correlated with antibody titers, skin thickness test, and production of IL-17A and IFN-γ in a whole-blood antigen stimulation assay (WBA)." (PMID 26375594, 2015). "Moreover, IL-17A neutralization resulted in a reduction of BALF leukocytosis which was primarily driven by a decrease in neutrophils." (PMID 35906257, 2022). "This synergistic response occurred only with the cows that developed the ovalbumin-specific inflammatory response, and there were significant correlations between milk leukocytosis and production of IL-17A and IFN-γ in a whole-blood ovalbumin stimulation assay." (PMID 27100324, 2016). "The magnitude of the synergistic milk leukocytosis correlated with the production of IL-17A and IFN-γ in milk and in vitro in the antigen-specific WBA, which provides circumstantial evidence that these two cytokines and the cells that produce them are behind the observed synergy." (PMID 27100324, 2016). "We found that the production of IL-17A and IFN-γ by circulating CD4+ lymphocytes of immunized cows correlated with the intensity of milk leukocytosis." (PMID 26375594, 2015). "CXCL8 concentrations declined sharply as soon as 16 hpi, in contrast with the concentrations of IL-17A and IFN-γ in quarters infused with ovalbumin alone or with LPS, which were low at 8 hpi, peaked at 16 hpi and thus augmented after the onset of milk leukocytosis." (PMID 27100324, 2016). "The cytokines IL-17A and IFN-γ were found in milk as soon as milk leukocytosis developed." (PMID 26375594, 2015). "In conclusion, we showed that mammary ASR, which manifested itself by an intense milk leukocytosis, was characterized by the production of IL-17A and IFN-γ but the absence of detectable TNF-α, with a low and inconsistent presence of IL-1β and IL-6." (PMID 23696826, 2013). "The subsequent milk leukocytosis was monitored to reveal the potential amplification of LPS-induced cell recruitment by sensitization to ovalbumin, and milk somatic cell counts (SCC) were correlated with the production of IL-17A and IFN-γ in an ovalbumin-specific whole blood stimulation assay." (PMID 27100324, 2016). "In a previous study we had found that the ovalbumin-specific production of IL-17A and IFN-γ correlated with the milk leukocytosis induced by the infusion of ovalbumin in the mammary gland of sensitized cows, and thus that the antigen-specific WBA could be used as a predictor of mASR." (PMID 27100324, 2016).
obliterative bronchiolitis (12 papers, 2013 to 2025). "IL-17a is a pro inflammatory cytokine released by effector CD4+CD25+ cells under certain inflammatory diseases and associated with other forms of bronchiolitis obliterans." (PMID 34941793, 2021).